BCL2 (BCL2 apoptosis regulator)
Diseases named in the same sentence as BCL2 in open-access papers (continued):
Sharing a sentence is not in itself a finding about the gene and the disease.
tumor (continued). "The intervention of Bax, Bcl-2, and caspase-3 gene expression is an important factor for determining tumor susceptibility to a given anticancer agent." (PMID 37570713, 2023). "Tumor size, lymph node involvement, and the Bax/Bcl-2 ratio were also higher in advance-stage tumors, which suggested that Bax/Bcl-2 ratio levels are associated with OSCC aggressiveness." (PMID 37408277, 2023). "Bcl-2 is well recognized as a family member of antiapoptotic B-cell lymphoma 2, which is implicated in tumor episodes including initiation, progression, apoptosis, and/or programmed cellular death and response to chemotherapy." (PMID 36982637, 2023). "Oncogenes account for cell survival and blockade of cell death, including BCL2, elucidating the underlying mechanism of tumour growth." (PMID 38203605, 2023). "The key variations include loss of PTEN, copy gain of HSP90AA1, and mutations in FOXO3 or BCL2, all of which are well established to contribute to tumor cell growth and survival." (PMID 36831263, 2023). "BCL2 is an anti-apoptotic protein that plays a key role in cell survival and has been implicated in tumor progression and resistance to therapy." (PMID 37176102, 2023). "Beyond BRAFV600E mutation, HC express the anti-apoptotic B-cell lymphoma 2 (BCL-2) protein, a well-studied inhibitor of cell death that sustains cell survival, tumor growth and cancer disease progression." (PMID 36968995, 2023). "Computational modeling of the mutations in the BCL2 gene responsible for apoptosis in tumor cells shows that the probability of mutations approaches the unity at the concentration of the cells with chromothripsis on the order of 10%." (PMID 38248163, 2023). "On the other hand, Bcl-2 expression is associated with tumor progression, including the occurrence of liver metastases in colorectal carcinoma and lymphovascular invasion in triple-negative breast carcinoma." (PMID 36766867, 2023). "This signaling pathway is responsible for several cellular functions, including cell proliferation and tumor growth, and coordinates the cell cycle and cell migration, in addition to causing changes in the Bcl-2 and BAD family of proteins." (PMID 37111343, 2023). "B-cell lymphoma-2 (Bcl-2)/adenovirus E1B 19 kDa-interacting protein 3 (BNIP3) reportedly apoptosis-inducing effects in tumour cells and is associated with the progression and treatment of multiple tumours." (PMID 37649051, 2023). "Bcl-2 inhibits cell death caused by various cytotoxic factors and plays a critical role in tumor cell apoptosis." (PMID 37250140, 2023). "We analyzed several genes associated with tumor growth and its resistance to treatment, including Bcl-2, Bax, Caspase-3, Survivin, EGFR, and VEGF." (PMID 35578215, 2022). "Bcl-2 and Bcl-xL are one apoptotic protein and have been associated with cell survival of tumor cells via blocking the mechanism of programmed cell death." (PMID 35708464, 2022). "Increased cell proliferation and inhibition of cell apoptosis cause tumor and cancer, whereas in cancer-bearing mice treated with CP-25 and 5-Fu, Bcl-2 were significantly downregulated as compared to cancer-bearing mice." (PMID 35154466, 2022).
tumor (continued). "In a study, the expression of GR induced by infecting GR-expressing adenovirus was shown to inhibit tumor growth in a xenograft model and lead to a significant decrease in Bcl-2 and Bcl-xL transcripts, causing apoptosis." (PMID 35631448, 2022). "For example, the BCL-2 F104L and F104C mutations were observed as venetoclax-resistance mutations in a mouse tumor model and induced drug tolerance in human cell lines." (PMID 36313628, 2022). "Increased Bcl-2 expression is linked with advanced-stage neoplasms and poor differentiation and is found to resist chemotherapy in many cancers." (PMID 35402265, 2022). "When FL cases were dichotomized based on the presence of BCL2 mutations in cfDNA and/or tumor tissue DNA, BCL2-mutated FL cases were associated with poor progression-free survival albeit not statistically significant (p = 0.05)." (PMID 35795062, 2022). "Stat3 target genes include Bcl-X and Bcl-2, both encoding anti-apoptotic proteins, and cooperation with c-Jun constitute yet another mechanism of interference with tumor cell apoptosis." (PMID 36376859, 2022). "The GSEA results revealed that the expression of ABCC1 was associated with tumor differentiation, nod-like receptor signal pathway, resistance to the bcl2 inhibitor up, and so on." (PMID 35342392, 2022). "On the other hand, we observed decrease in survival-associated genes such as Bcl2 and Bcl-XL in tumor tissues of p40 mAb-treated PDX mice." (PMID 35053375, 2022). "In this regard, we demonstrated that Bcl-2 modulates in vitro and in vivo tumor progression-associated properties and angiogenesis through regulation of microRNA and transcription factors 4-14." (PMID 35265218, 2022). "In tumor cells, the loss of spt16 led to the downregulation of Bcl2, a negative regulator of apoptosis, thereby inducing tumor cell growth defects." (PMID 36421975, 2022). "Surprisingly, Cur@affi-F/GQs significantly enhance the expression and activity of apoptosis-associated proteins in Bcl-2/Bax-caspase 8, 9-caspase 3 apoptotic pathway, which is the main factor in the death of tumor cells induced by FUdR." (PMID 35215023, 2022). "The B-cell lymphoma-2 (Bcl-2) protein family are pivotal regulators in apoptosis and is highly associated with tumor progress." (PMID 36080223, 2022). "Recently, the loss of NOXA, a B-cell lymphoma 2 (BCL2) family protein in B cell malignancies was found to be the major regulator of resistance to CAR T cell therapy by impairing the apoptosis of tumor cells." (PMID 35617812, 2022). "In a prior in vitro study, restoration of miR-16 levels was shown to inhibit tumor cell proliferation, linked to the downregulation of Bcl-2 and CCND1." (PMID 35205318, 2022). "Dysregulation of Bcl-2 proteins occurs during tumor development and is associated with cellular resistance to chemotherapy treatments." (PMID 35912268, 2022). "The finding that MCL-1, an inhibitor of apoptosis, and BCL-2 levels are modulated by the tumor-associated microenvironment has stimulated further investigation focused on MCL-1 inhibition." (PMID 36212502, 2022). "Bcl-2 overexpression will increase the mutation opportunities of other genes, resulting in the deterioration of normal cells into tumor cells." (PMID 36618947, 2022). "Numerous tumours have been shown to have an increase in the ratio of anti- to pro-apoptotic Bcl-2 proteins, which has been linked to tumour cell survival and apoptosis resistance." (PMID 36620544, 2022). "We herein demonstrate that BCL-2 inhibition is a promising method to induce tumor cell abrogation in this high-risk cohort." (PMID 35778418, 2022). "Several of these changes are anti-apoptotic in function such as PTEN−/−, Bcl-2 and Bcl-xL overexpression, while others such as the activating KRas mutation alter migration and in vivo tumor formation." (PMID 35406479, 2022).
tumor (continued). "In head and neck cancer patients tumor-associated CEC express significantly higher level of Bcl-2, that is directly correlated with metastatic status, since they co-migrated with tumor cells to lung." (PMID 35992829, 2022). "Venetoclax is currently the only approved BCL-2 inhibitor that can cause tumor cells to produce apoptosis and achieve the effect of killing tumors." (PMID 35741053, 2022). "When we evaluated mutations detected in cfDNA and/or tumor tissue DNA, mutations in the BCL2 gene predicted a poor overall survival (p = 0.0042)." (PMID 35795062, 2022). "Increasing studies have found that overexpression of Bcl-2 is a hallmark of cancer and contributes to tumor cell survival as well as the resistance to therapy in MM." (PMID 34980181, 2022). "The prognostic importance of pretreatment PROs remained for both OS and PFS even after adjusting for IPI score, and other key variables such as cell of origin, BCL2 mutation status, and total metabolic tumor volume." (PMID 35322932, 2022). "In contrast to Bcl-2, Bcl-xL is associated with higher tumor grade and increased number of positive nodes and is a predictor of worse overall survival." (PMID 35053443, 2022). "Further, we found that the expression of BCL-2 downstream of JAK2/STAT3 was also reduced, and BCL-2 was associated not only with apoptosis but also with the infiltration of immune cells in the immune microenvironment of the tumor." (PMID 36582521, 2022). "BCL-2 is one of the most important antiapoptotic genes, and although it facilitates tumour cell survival and proliferation, overexpression of BCL-2 has been consistently associated with good prognosis." (PMID 34316706, 2021). "As for Bcl-2, there was also a significant association between its high level with advanced tumor stage, lymph node involvement and distant metastasis." (PMID 34181356, 2021). "Lower miR-148a gene expression level and higher Bcl-2 concentration were found to be associated with advanced tumor stage, lymph node involvement and distant metastasis." (PMID 34181356, 2021). "For comparison, the literature data are more consistent and coherent for Bcl-2, another major inhibitor of apoptosis, whose expression is associated with good-prognosis factors such as ER+, low grade, and smaller tumor size." (PMID 34199946, 2021). "In the treatment of neoplasms associated with proteins from the BCL-2 family or BCL-2 expression, BCL2 inhibitors such as venetoclax or navitoclax are used." (PMID 34575992, 2021). "Conversely, loss or downregulation of the pro-apoptotic BCL-2 members have been observed in many tumor types." (PMID 33799470, 2021). "A high expression of BCL-2 seems to be associated with high sensitivity to venetoclax in many tumor models." (PMID 33799470, 2021). "High levels of Bcl-2 expression have also been correlated with tumor severity, which is associated with unfavorable histology, MYCN amplification, and poor prognosis." (PMID 34832966, 2021). "As expected, we found that excessive ROS caused by CoFe2O4-QDs significantly downregulated the expression of PI3K/AKT pathways and therefore cause tumor cell apoptosis via activating Bax but inactivating Bcl-2 protein." (PMID 34322770, 2021). "Multiple studies have shown high BCL-2 tumor cell expression associated with venetoclax sensitivity; however, this is not uniformly observed, suggesting this is not the only factor determining response." (PMID 35008216, 2021). "Bcl-2 is considered anti-apoptotic as it is proficient suppressor of apoptosis and its elevated levels are usually associated with tumor cell resistance to apoptosis." (PMID 34832895, 2021).
tumor (continued). "It targets the sequence around translation initiation of the bcl-2 mRNA inhibiting its translation, resulting in decreased levels of the bcl-2 protein, an apoptotic inhibitor expressed in some types of cancer and linked to tumor drug resistance." (PMID 33922974, 2021). "Overexpression of Bcl-2 antiapoptotic proteins can prevent cell apoptosis, ultimately causing tumor." (PMID 34512772, 2021). "MSCs also produce IL-6 that causes tumor cells to resistance to chemotherapy through upregulation of BCL-2 and activation of STAT-3." (PMID 33579346, 2021). "This is the case, for example, of the fructose-related downregulation of Bcl2, a protein with antiapoptotic activity, which is a hallmark of many cancerous cells that present a deficit in apoptosis that facilitates tumour growth." (PMID 34650394, 2021). "Intriguingly, we found inferior OS in the high BCL-2 patient tumour samples, which unexpectedly was associated with the epithelioid subtype that generally has a better prognosis." (PMID 33298868, 2020). "Tumor cells can acquire resistance to apoptosis by Bax downregulation or mutation and Bcl-2 upregulation." (PMID 32901694, 2020). "Half of all tumor types present overexpressed antiapoptotic Bcl-2 proteins and the loss of proapoptotic factors, resulting in resistance to apoptotic stimuli, including anticancer therapeutic drugs." (PMID 33053881, 2020). "Briefly, berberine is able to disrupt the B-cell Lymphoma-2/Bcl-2 associated protein X (Bcl-2/Bax) ratio, which in turn decreases the mitochondrial membrane potential of tumor cells." (PMID 33521059, 2020). "Taken together, these data suggest that MOES MVs induce a reduction in cell growth and an increase in apoptosis in tumor cell lines that is associated with a significant downregulation of BCL2 protein expression." (PMID 32550010, 2020). "We found that higher BCL2 mRNA and protein level were associated with older age, higher tumor stage, and higher Gleason score." (PMID 32685011, 2020). "Circulating tumor-associated ECs that express Bcl-2 have been implicated in protecting tumor cells from anoikis and enhancing lung metastasis." (PMID 32375250, 2020). "This assumption was based on the fact that the lesion shows overexpression of proliferative markers and Bcl-2, in addition to loss of heterozygosity or methylation of tumor suppressor genes and mutation of the PTCH1 gene." (PMID 33374329, 2020). "In CLL, this was attributed to a tumor-specific increase in apoptosis, associated with a decreased BCL2/BAX ratio." (PMID 32517377, 2020). "TSLP caused the release of CCL17 by tumor cells with recruitment of eosinophils that in turn induced proliferation and restricted tumor cell apoptosis through up-regulation of Ki-67 and Bcl-2, respectively and of proangiogenic factors." (PMID 33042121, 2020). "It overcomes the apoptosis resistance and cell proliferation caused by the high expression of BCL2 in tumor cells." (PMID 33292251, 2020). "The incomplete expression of dihydropyrimidine dehydrogenase and total deficiency of Bcl-2 are considered to be the main underlying causes of such extraordinary chemosensitivity and so severe a tumour lysis phenomenon." (PMID 32582369, 2020). "Since COX-2 upregulates Bcl-2 expression, it leads to resistance to apoptosis in UC-associated neoplasia." (PMID 31102112, 2019). "We also show that tumor and normal cells with the variant express higher levels of BCL2 protein, a phenomenon that we validated in an independent cohort of patients." (PMID 31044156, 2019). "Positive immunohistochemical staining to Bcl-2 was cytoplasmic, and observed in neoplastic cells as well as some of the lymphocytes in tumor-associated lymphohistiocytic inflammation." (PMID 30630524, 2019). "Tumor samples displayed 142 differentially expressed genes, mostly upregulated (89%), including those encoding for CyclinD1 and the anti-apoptotic protein BCL2." (PMID 31035408, 2019).
tumor (continued). "BCL2 (B-cell lymphoma 2) expression is elevated in many tumours, including ALL, and has been associated with an adverse prognosis." (PMID 29977016, 2019). "In the global cohort (180 FMCs), Bcl-2 positivity was negatively associated with distant metastasis (p = 0.015), squamous differentiation (p = 0.002), and the magnitude of tumor-associated inflammation (p = 0.038)." (PMID 30630524, 2019). "Connexin 43 (Cx43) protein and its cell-communication channels have been assigned tumor suppressor functions while the anti-apoptotic Bcl-2 (B-cell lymphoma-2) protein has been associated with negative prognostic significance in cancer." (PMID 31766723, 2019). "One author had demonstrated that Bcl-2 overexpression seems to be associated with advanced histologic grade, resulting in a more aggressive tumor." (PMID 31754362, 2019). "Low Bcl-2 expression was observed with advanced tumor stage; however this association didn’t reach the level of significance." (PMID 31754362, 2019). "In our study using tumor cell lines, we found an inverse association between Cx43 and Bcl-2 protein expression in the FFPE HNSCC tissue samples." (PMID 31766723, 2019). "Caspase-3 is a protein associated with cell apoptosis, and it is considered a tumor suppressor because it acts downstream of Bax/Bcl-2 control and plays a key role in the execution of apoptosis." (PMID 31028131, 2019). "AX-I-3b treatment caused mitochondria-dependent apoptotic pathway in mouse tumor cells through up-regulating the Bax/Bcl-2 ratio." (PMID 31601012, 2019). "Resistance to apoptosis of tumor cells involves several mechanisms including overexpression of anti-apoptotic proteins (Bcl-2) or downregulation/mutation of pro-apoptotic proteins such as Bax." (PMID 31551765, 2019). "We were also able to show that blocking of Bcl-2 by ABT-727 causes a decrease in the invasion capacity of the tumor cells studied." (PMID 31759362, 2019). "The results of this analysis show that a single variant in the BCL2 gene is significantly associated with resistance to paclitaxel in multiple tumor types." (PMID 31044156, 2019). "PTEN and p-AKT are associated with cell apoptosis, and play a crucial role in tumor progression, so the mRNA level of the Caspase-9, Caspase-3, Bcl-2 and Bax, which are considered as the dominant role during apoptosis, were detected by qRT-PCR." (PMID 31666604, 2019). "Several studies have shown that the overexpression of antiapoptotic proteins including cIAP-2, cFLIPs, Bcl-2, and Bcl-XL in tumor cells has been associated with the inhibition of TNF-α-induced apoptosis." (PMID 31766230, 2019). "As with anti-apoptotic Bcl-2 proteins, loss of pro-apoptotic proteins can cooperate with other oncogenes to accelerate tumour development and progression." (PMID 31681471, 2019). "BCL-2 over expression was positively associated with tumor grade and ER/PR, and negatively with tumor size." (PMID 31286981, 2019). "Overexpression of anti-apoptotic proteins such as Bcl-2, Bcl-XL, and Mcl-1 has been associated with drug resistance in human tumor cell lines, including NHL cells." (PMID 31798573, 2019). "Some clinical trials have associated Bcl-2 expression with favourable prognosis and others have shown no statistical correlation between Bcl-2 expression and prognostic factors like tumor stage and grade." (PMID 31754362, 2019). "In this study, we showed that RBBP6 is highly expressed in tumour-associated stroma, which was directly related to apoptosis levels and indirectly associated with Bcl-2 expression." (PMID 30886526, 2019).